IL33 (interleukin 33)
Diseases named in the same sentence as IL33 in open-access papers (continued):
Sharing a sentence is not in itself a finding about the gene and the disease.
viral infection (108 papers, 2012 to 2026). "IL-33 functions as an alarmin released from airway epithelial and endothelial cells when they experience stress or injury caused by inhaled allergens, viral infections, tobacco smoke, or pollutants." (PMID 40732309, 2025). "Despite this, the IL-33/ST2 signaling pathway has well-defined roles in T cell activation during viral infection, with CD8+, CD4+, and Treg cells implicated." (PMID 37983247, 2023). "Viral infections are the leading cause of hospitalizations and emergency care for asthmatic individuals, and IL-33 is elevated in the serum and sputum of asthmatics following an acute exacerbation." (PMID 34266437, 2021). "The release of IL-33 alarmin by pneumocytes and endothelium, in response to cell damage caused by viral infection, triggers a cascade of events in fibroblasts, alveolar membrane, coagulation and immune system." (PMID 34441830, 2021). "The release of IL-33 can occur as a consequence of tissue damage associated with allergic inflammation or viral infection, and during toxoplasmosis, IL-33 levels correlated closely with levels of parasite replication and host cell lysis." (PMID 33929319, 2021). "Recent studies in mice and humans have implicated the importance of IL-33 in the development of Th2 inflammation during RV infection, thus providing a possible mechanistic link between viral infections and eosinophilic inflammation." (PMID 30174671, 2018). "Therefore, the contribution of IL-33 to beneficial or pathogenic responses to viral infection deserves further characterization." (PMID 37983247, 2023). "Therefore, our future studies will evaluate lung viral titers and pathology in a viral infection model to shed light on potential clinical challenges associated with reducing IL-33." (PMID 34266437, 2021). "However, during mucosal infection with herpes simplex virus type 2, the systemic administration of IL-33 increases susceptibility to viral infection, resulting in severe mortality and morbidity." (PMID 31509992, 2019). "This skewed expression of each splice variant may partially explain why IL-33 has the ability to amplify type 2 responses during viral infection in asthmatic individuals while having a protective role in healthy individuals." (PMID 30174671, 2018). "While an early IL-33 response associated with suppression of viral replication may be desirable during viral infection, during vaccination this alarmin was associated with decreased viral replication and consequential mucosal IFN responses, limiting peripheral antibody responses." (PMID 38052824, 2023). "Second, we did not test which cell types including ILC2 may produce type 2 cytokines in Tollip deficient mice with increased IL-33 release as previous studies have demonstrated an important role of ILC2 in IL-33-mediated type 2 cytokine expression during viral infection." (PMID 38124753, 2023). "The types of damage triggering IL-33 release include mechanical injury, scratching, bacterial, fungal, or viral infections, contact with allergens, and induction of necrosis." (PMID 41155460, 2025). "During viral infections, IL-33 promotes type 1 responses in CD4+ Th1 and CD8+ T cells, which transiently express ST2 upon antigen recognition and stimulation with IL-12, including the production of IFNγ and TNF." (PMID 41087719, 2025). "During fungal or viral infections, IL-33 sustains Treg cell suppressive functions, whereas IL-1 promotes the acquisition of a Th17 phenotype and antipathogen responses." (PMID 41087719, 2025). "Considering that IL‐33 plays crucial roles in type 2 immunity, inflammation, and viral infection, we further explored the effects of IL‐33 on immune infiltration based on public database." (PMID 38737470, 2024). "The data also indicate that GPNMB is context dependent with the present function set in the matrix of timing for GPNMB+ moDC and IL-33+ basal ESC interaction at 1–2 weeks after viral infection." (PMID 39052353, 2024).
viral infection (continued). "This study defines IL-33 as an oligodendrocyte-derived survival factor for microglia, and suggests that IL-33 is required during viral infection to promote normal microglial activation." (PMID 37983247, 2023). "Accumulating evidence suggests that Interleukin-33 (IL-33), a member of the IL-1 family, has crucial roles in tissue homeostasis and repair, type 2 immunity, inflammation, and viral infection." (PMID 37296602, 2023). "IL-33 is expressed at basal levels in the airway epithelium, but its expression and secretion can be upregulated during viral infections." (PMID 37631998, 2023). "While the role of IL-33 SNPs in viral infections, particularly COVID-19, remains largely unexplored, previous studies have indicated a protective effect of this SNP in other diseases, such as rheumatoid arthritis and cardiovascular conditions." (PMID 37761861, 2023). "After tissue damage, cellular stress, allergen exposure, or viral infection, full-length IL-33 is quickly and passively released and “alarms” the immune system by activating group II innate lymphocytes (ILC2s) and other immune cells such as mast cells." (PMID 38082335, 2023). "It will be of interest to distinguish these differential roles for IL-33 in anti-viral immunity in healthy individuals and patients with severe viral infections." (PMID 38052824, 2023). "In the lung, this is further augmented by epithelial release of IL-33 upon viral infection to further boost Tc1 plasticity and trigger an episode of increased symptom severity." (PMID 37612281, 2023). "As cell death by necrosis, mechanical injury, or viral infection is required for IL-33 release from other cell types, it is possible that excess TGFβ-induced IL-33 is degraded in the proteasome of HLFs rather than being released." (PMID 36949463, 2023). "IL-33 is an alarmin with many roles including tissue homeostasis and repair, type 2 inflammation and viral infections." (PMID 36366528, 2022). "In view of the enhanced anti-viral response mediated by IL-33, we next investigated the impact of IL-33 on viral infection." (PMID 36366528, 2022). "Following the local epithelial damage due to viral infection, production of IL-25, IL-33, and TSLP increases, which stimulates ILC2s, and as a result, T2 inflammation is induced." (PMID 36326393, 2022). "Various studies have reported protective roles for IL‐33 in liver injury induced by concanavalin A,45 ischemia‐reperfusion, virus infection, and nonalcoholic steatohepatitis." (PMID 35593197, 2022). "It is known that viral infections increase the expression of airway epithelium-born cytokines such as IL-25, IL-33, and thymic stromal lymphopoietin (TSLP) and stimulate ILC2 responses." (PMID 36326393, 2022). "Previous studies demonstrated an enhanced expression of IL-33 after viral infections (including tumor viruses), and in immunoresponses in different malignancies." (PMID 35409061, 2022). "Depending on the type of viral infection IL-33 has either a protective or detrimental role and appears to be highly specific depending on the virus." (PMID 36366528, 2022). "These discoveries can further serve as a baseline resource for the development of therapeutic targets for diseases in which IL-33 signaling plays a role, including bacterial and viral diseases and cancers." (PMID 35011700, 2022). "In cooperation with IL-12 produced in response to LCMV/MCMV viral infection, IL-33 increases the expansion of activated CD8+ T cells and promotes secretion of antiviral cytokines, such as IL-10 and IFN-γ." (PMID 36291105, 2022). "Conversely, IL-33 has shown to enhance cytotoxic and memory T cell responses to virus infection and vaccine challenge." (PMID 33857419, 2021). "In the context of viral infection, it is generally accepted that full-length IL-33 is released as a bioactive form by cells that undergo necrosis and necroptosis, as well as by cells that undergo cytolysis or release their nuclear contents." (PMID 34960788, 2021).
viral infection (continued). "Taken together, these data suggest that more investigations are warranted to determine the role of IL-33/ST2 signaling in parasitic/viral infection." (PMID 34079543, 2021). "IL-33 is constitutively expressed by AECs, although the source of IL-33 during viral infection seems to be host-dependent." (PMID 34960788, 2021). "This contrasts the improved memory T‐cell formation when using the alarmin IL‐33, that is released upon cell damage after viral infections, as an adjuvant." (PMID 34003499, 2021). "In response to pathogen recognition, allergen exposure or viral infection, epithelial cell-derived cytokines such as IL-25 and IL-33 are released." (PMID 34220812, 2021). "Aside from its role in viral infection, IL-33 is also important in the host defense against bacterial infection post-IAV infection." (PMID 34960788, 2021). "More importantly, IL-33 has also been shown to participate in lung epithelium response to viral infection and to decrease antiviral innate immunity in this organ." (PMID 34441830, 2021). "Alveolar epithelial IL-33 is upregulated by a number of pathologic stimuli including nematode or viral infections, and exposure to cigarette smoke, ozone, cysteine proteases, uric acid, bleomycin, or allergens." (PMID 32903501, 2020). "Another important feature of IL‐33 during viral infection is the activation of ST2+Th1 cells, which also plays a role in antiviral immunity." (PMID 32566227, 2020). "These cell populations, increased in CD duodenum, are known to play an important role in CD pathology, and are also targeted by free IL-33 on viral infections and certain tumor environments." (PMID 33133101, 2020). "During viral infection, IL‐33 can significantly enhance clonal expansion of ST2+CD8+T and NK cells to induce a cytotoxic response against a viral load in mice." (PMID 32566227, 2020). "ILC2s are potently activated by epithelial cell-derived IL-25 and IL-33, both of which are released in response to allergens, viral infection, and epithelial injury." (PMID 30654796, 2019). "IL-33 remained unchanged upon viral infection in both groups when compared to the corresponding UV-inactivated control, although the overall level of IL-33 was higher in the HDM-sensitized group." (PMID 31640701, 2019). "This is seen in models of viral infections, where IL-33 plays ambiguous roles on the T cell response." (PMID 30949175, 2019). "Overall, these findings suggest that elevated IL-12p40 levels and DC recruitment by exogenous IL-33 injection prior to viral infection can enhance CTL responses against the influenza virus." (PMID 31509992, 2019). "When mice are infected with RSV, IL-33 is rapidly released in the early phases of viral infection in the lung." (PMID 30949175, 2019). "New evidence has emerged that Th1 effector cells can transiently express ST2 during experimental viral infection and that Th1 effector cell differentiation and cytokine production is dependent on the IL-33/ST2 axis." (PMID 30174671, 2018). "During viral infection, IL-33/ST2 axis amplifies the expansion of NK cells and enhances host defense." (PMID 30483263, 2018). "In a COPD mouse model and in vitro airway epithelial cells, increases of IL-33 have been also shown, especially during viral infection or after cigarette smoke exposure." (PMID 29587772, 2018). "Overall, The IL-33/Treg axis seems to be a promising route for the development of future therapies in viral infections." (PMID 28448566, 2017). "The pro-Th2 cytokine IL-33 is now emerging as an important Th1 cytokine-IFN-γ inducer in murine CD4+ T cells that is essential for protective cell-mediated immunity against viral infection in mice." (PMID 26688508, 2016). "Recent reports have suggested that alveolar macrophages are important sources of IL-33 in the lung upon helminth and viral infections." (PMID 24551140, 2014). "ILC2s and HSPCs paly an important role in IL-33-mediated innate responses to injury, parasitic and viral infection, and allergic inflammation." (PMID 23653627, 2013).
viral infection (continued). "IL-33 has been reported to be released from necrotic cells after viral infections; IL-33 activates in turn CD8 + T cells (CTLs), to promote virus control." (PMID 23423835, 2012). "The IL-1 family cytokine IL-33 is involved in the induction of airway inflammation in allergic patients and after viral infection." (PMID 22738676, 2012). "The IL-1 family member IL-33 is a pleiotropic cytokine that has been implicated in the induction of airway hyperresponsiveness (AHR) in allergic patients and after viral infection." (PMID 22738676, 2012). "A mimetic of double-stranded RNA increased IL-33 production in fibroblasts, suggesting that both bacterial and viral infections may upregulate IL-33 production in skin cells." (PMID 41155460, 2025). "Increased levels of CCL4 (Japanese encephalitis virus, West Nile virus [WNV]) and IL-33 (WNV) have been linked to neuroinflammation following virus infection, but no changes in their levels were observed in TBEV-infected CSF samples compared to controls." (PMID 40517242, 2025). "The findings suggest that IFN-γ- and IL-33-induced inflammatory responses during viral infection may induce eosinophil activation in overall patients with COPD, particularly during exacerbations." (PMID 39439801, 2024). "Sufficient amounts of IL-33 are released from airway epithelial cells during viral infection." (PMID 39439801, 2024). "This suggests that IL-33 signaling may drive a subset of microglial functions related to survival and disease tolerance in the context of viral infection, and that in its absence microglia may still participate in viral control." (PMID 37983247, 2023). "For the first time, we investigated IL-33 release in HDM-challenged mice with viral infection." (PMID 38124753, 2023). "IL-33, an upstream regulator of IL-13 in vivo, can be induced during viral infection." (PMID 38124753, 2023). "Given that current treatments for viral infections are based on preventive measures such as yearly vaccination, targeting IL-33 might represent a novel strategy to halt or reduce the dramatic effects of COPD exacerbations due to these pathogens." (PMID 37240045, 2023). "While the exact mechanism remains unclear, it suggests that ATP and IL-33 may utilize differ pathways to regulate viral infection." (PMID 38124753, 2023). "Our data demonstrated that Tollip deficiency may contribute to excessive lung type 2 inflammation by amplifying the release of ATP during viral infection and subsequently increasing the release of IL-33." (PMID 38124753, 2023). "IL-33 has been implicated in glycolysis in the activation of CD8+T cells and, of note, is also important in maintaining mitochondrial dynamics during the differentiation of memory CD8+T cells following virus infection." (PMID 35979357, 2022). "In this study we investigated the global response of MCs to IL-33 stimulation and whether this has a functional consequence during viral infection." (PMID 36366528, 2022). "In addition, IL-33 plays an important role in host response to various viral infections including human immunodeficiency virus (HIV), dengue virus (DENV) and HCV." (PMID 35056005, 2022). "In this study we investigated the global response of MCs to IL-33 stimulation and determined whether this had a functional consequence during viral infection." (PMID 36366528, 2022). "Indeed, in humans, during the 2009 influenza pandemic it was noted that asthmatics, who intrinsically produce higher levels of IL-33 in response to viral infection, had less chance to develop secondary bacterial pneumonia." (PMID 34960788, 2021). "In other contexts, IL-33 cooperates with IL-12 produced in response to LCMV/MCMV viral infection." (PMID 35011670, 2021). "IL-33 drives an exacerbated Th-1-cell-like inflammatory response to viral infection." (PMID 33722239, 2021).
viral infection (continued). "IL-33 and its receptor ST2 are strongly associated with the development of AD disease triggered by allergen exposure, irritants, scratching, and the bacterial and viral infections seen in this condition." (PMID 34531749, 2021). "Diverse roles of IL-33 during viral infections have been identified." (PMID 33857419, 2021). "IL-33 has been found to positively correlate with IL-1β expression, implying that IL-33 might play a role in the proinflammatory response in virus infection." (PMID 34079543, 2021). "IL-33, which is participated in viral infection, was increased in SMG." (PMID 33928105, 2021). "IL-33 is present in the nucleus of epithelial cells and is released from epithelial cells in response to fungi such as Alternaria, protease activity of HDMs, or viral infection." (PMID 32397396, 2020). "Interestingly, IL-33 and sST2 transcript correlated with IRF-1 mRNA levels, which was found to be essential for IL-33 production under viral infections in endothelial cells." (PMID 33133101, 2020). "IL-33, which is released primarily from the epithelial cells in the lung in response to danger signals (e.g., allergens, viral infection), induces the release of type 2 cytokines, including IL-13, from several innate immune cells in the lung that then promote lung inflammation." (PMID 31118931, 2019). "Thus, IL-33 plays a role in not only type 2 immunity but also in type 1 immunity against bacterial and viral infections." (PMID 31509992, 2019). "Interestingly, although the effect of IL-33 was originally thought to be a determinant of type 2 immune responses, it was shown to also favor the expansion of NK and NK T cells during viral infections." (PMID 30949175, 2019). "Furthermore, we observed that the injection of exogenous IL-33 prior to viral infection increased the survival of influenza-infected mice and induced ILC2 recruitment into the lung." (PMID 31509992, 2019). "IL-33 is also involved in tissue repair after viral infection." (PMID 29977243, 2018). "While these studies explored pulmonary responses to exogenously administered IL-33, carbon nanotubes and viral infection, our findings provide additional evidence of a similar link between acute pulmonary ENM exposure and subsequent inflammatory mechanisms with systemic microvascular consequences." (PMID 30413212, 2018). "In the current study, we examined whether oxidative stress, which participates in the pathogenesis of COPD, affects the expression of IL-33 in airway epithelial cells and also evaluated the effect during viral infection." (PMID 29587772, 2018). "In addition, we demonstrated the possibility that oxidative stress augments the expression of IL-33 during viral infection and is involved in the expression of IL-33 in HBECs from COPD patients." (PMID 29587772, 2018). "To determine whether oxidative stress augments IL-33 expression during viral infection, we investigated the effect of H2O2 on the expression of IL-33 in poly (I:C)-treated NCI-H292 cells." (PMID 29587772, 2018). "Thus, IL-33 augments neutrophilic airway inflammation in certain situations, such as when viral infections accompany necrotic tissue damage." (PMID 30176857, 2018). "Thus, here we provide evidence that following viral infection, IL-33 is produced in the CNS to counteract the deleterious effects of pro-inflammatory cytokines IFN-γ and TNF-α, as well to shift macrophage response to a M2-protective phenotype." (PMID 27334012, 2016). "As such, in the IL-12-dominant cytokine milieu, for instance, in the pro-inflammatory conditions or bacterial/virus infection, secreted IL-33 may potentiate IL-12-mediated Th1 cell differentiation." (PMID 26688508, 2016). "However, limited data is available about the association of IL-33 and ST2 expression in viral diseases." (PMID 24058536, 2013).